DEGS2 (delta 4-desaturase, sphingolipid 2)
Description:
Bifunctional enzyme which acts both as a sphingolipid delta(4)-desaturase and a sphingolipid C4-monooxygenase.
Synonyms: C14orf66; DES2; FADS8
Tractability: Antibody: UniProt predicts a signal peptide or a membrane-spanning region.
Gene: Protein-coding gene on chromosome 14 (100,143,957 to 100,159,645, reverse strand). Ensembl gene ENSG00000168350.
Subcellular location: Endoplasmic reticulum membrane
Subcellular location (Human Protein Atlas): Nucleoli; Nucleoplasm
Pathways (Reactome):
Metabolism: Sphingolipid de novo biosynthesis
Gene Ontology:
Molecular function: sphingolipid C4-monooxygenase activity; sphingolipid delta-4 desaturase activity; catalytic activity
Biological process: ceramide biosynthetic process; sphinganine metabolic process; sphingolipid biosynthetic process; lipid metabolic process
Cellular component: endoplasmic reticulum membrane; membrane
Genetic constraint (gnomAD): Loss-of-function variants: 16 observed, 21.6 expected, observed/expected ratio (o/e) 0.74, 90% interval 0.5 to 1.12. The upper end of that interval is the gene's LOEUF score, 1.12, which puts it in group 4 of 6, group 1 being the genes least tolerant of losing a copy. Missense variants: 370 observed, 428.4 expected, observed/expected ratio (o/e) 0.86, 90% interval 0.79 to 0.94. Synonymous variants: 203 observed, 204.23 expected, observed/expected ratio (o/e) 0.99, 90% interval 0.89 to 1.12.
Homologues: Orthologues: chimpanzee DEGS2 (99% identical), macaque DEGS2 (97% identical), pig DEGS2 (93% identical), mouse Degs2 (86% identical), dog DEGS2 (85% identical), guinea pig DEGS2 (84% identical), rat Degs2 (80% identical), zebrafish degs2 (73% identical), tropical clawed frog degs2 (67% identical), Drosophila melanogaster ifc (57% identical), Caenorhabditis elegans ttm-5 (54% identical), Caenorhabditis elegans F33D4.4 (49% identical). Paralogues in human: DEGS1 (63% identical).
Diseases named in the same sentence as DEGS2 in open-access papers:
DEGS2 is named in the same sentence as 28 diseases in open-access papers, as found by Europe PMC text mining. Sharing a sentence is not in itself a finding about the gene and the disease. The quoted sentences say what the papers report.
colorectal cancer (5 papers, 2021 to 2023). A primary or metastatic malignant neoplasm that affects the colon or rectum. "Lentivirally transduced MC38 colorectal cancer cells, sorted on an mCherry reporter, demonstrated decreased expression of the mutant (N189D) compared to wild-type DEGS2." (PMID 37589563, 2023). "For example, we observed the enhanced DEGS2's consumption amount of dhCer as reported in colorectal cancer, the significantly inhibited salvage pathway by overexpressed CERS5, and the activated sphingosine generation pathway by overexpressed ASAH1." (PMID 37999228, 2023). "m6A mRNA methylation of DEGS2, a key ceramide-synthesizing enzyme, regulates the Cer metabolism to control cell proliferation in colorectal cancer." (PMID 35217651, 2022). "Recently, Guo and collaborators found the role of m6A modification on DEGS2 in colorectal cancer and suggested that inhibited m6A promotes DEGS2 expression and dysregulated lipid metabolites, contributing to colorectal cancer." (PMID 35186927, 2022).
schizophrenia (3 papers, 2015 to 2022). A major psychotic disorder characterized by abnormalities in the perception or expression of reality. "Our findings demonstrate that a SNP showing genome-wide association study significant association with cognition in schizophrenia is also associated with regulation of DEGS2 expression, implicating a molecular mechanism for the clinical association." (PMID 25871975, 2015). "Although the DEGS2 gene general function in the nervous system is unknown, a genome-wide association study of cognitive dysfunction in schizophrenia patients found an association with missense mutations in the DEGS2 gene." (PMID 35439525, 2022). "From birth onward, the DEGS2 gene is most abundantly expressed in the dorsolateral prefrontal cortex (DLPFC) that is a major component of the high-order associative cortex related to both schizophrenia and cognitive functions." (PMID 29312019, 2017). "Further research is needed to clarify the role of glutamate network and DEGS2 gene expression in the pathogenesis of ID of schizophrenia." (PMID 29312019, 2017). "To address these questions, we examined DEGS2 messenger RNA using next-generation sequencing in postmortem dorsolateral prefrontal cortical tissue from a total of 418 Caucasian samples including patients with schizophrenia, bipolar disorder and major depressive disorder." (PMID 25871975, 2015).
ischemic stroke (2 papers, 2015 to 2025). A stroke disorder caused by obstruction of blood flow to the brain, due to thrombotic (local blood clot formation) or embolic (due to a blood clot or other material traveling from another site) event. "Single-gene GSEA revealed that the identified signature genes (Pip5k1c, Nlgn2, Fzd2, Cd86, Agpat1, and Degs2) converge on neuroinflammatory and apoptotic pathways critical in ischemic stroke pathogenesis." (PMID 40520774, 2025). "Among the downregulated genes, Gpr88, Rgs9, Enthd1, Olr59, P2ry12, Degs2, Pde10a, Neu2, Adora2a, and Slc22a6 were found to demonstrate significant downregulation in pathological phase of ischemic stroke." (PMID 25861363, 2015). "The results demonstrated that, in comparison to the control group, the expression of Pip5k1c, Nlgn2, Fzd2, Cd86, Agpat1, and Degs2 showed a downward trend with an increase in the onset time of ischemic stroke, and the decrease was most significant in the MCAO_12 h group (p < 0.01)." (PMID 40520774, 2025).
major depression (2 papers, 2015 to 2025). "Previous studies have demonstrated that Degs2 expression is reduced in patients with major depression." (PMID 40520774, 2025).
psoriasis (2 papers, 2023 to 2024). An autoimmune condition characterized by red, well-delineated plaques with silvery scales that are usually on the extensor surfaces and scalp. "We next examined the effects of Degs2 disruption on psoriasis pathology using a psoriasis model induced by imiquimod." (PMID 36907437, 2023).
cerebral infarction (1 paper, 2025). An ischemic condition of the brain, producing a persistent focal neurological deficit in the area of distribution of the cerebral arteries. "We further analyzed the expression differences of Pip5k1c, Nlgn2, Fzd2, Cd86, Agpat1, and Degs2 between the cerebral infarction at 3, 6, and 12 h and the control group." (PMID 40520774, 2025). "The AUC values of Pip5k1c, Nlgn2, Fzd2, Cd86, Agpat1, and Degs2 were all 1, suggesting that Pip5k1c, Nlgn2, Fzd2, Cd86, Agpat1, and Degs2 have good sensitivity and specificity for the diagnosis of cerebral infarction." (PMID 40520774, 2025).
cholestasis (1 paper, 2025). Impairment of the bile flow caused by obstruction within the liver, or outside the liver in the bile duct system. "We found that enzymes contributing to CER production were upregulated by cholestasis, including DEGS2 in humans and Smpd3 and Cers3 in mice, indicating activation of CER generation by cholestasis." (PMID 40025008, 2025).
cognitive deficits (1 paper, 2015). "Ten SNPs in low-to-high LD (r2=0.26–0.75) with rs7157599 (related to cognitive impairment) were also associated with DEGS2 expression (P<0.05)." (PMID 25871975, 2015).
colitis (1 paper, 2023). Inflammation of the colon. "In this study, we report that DEGS2 is necessary for restoration of intestinal homeostasis and provide a phenotypic characterization of the colitis phenotype caused by loss of DEGS2 function." (PMID 37589563, 2023). "Using a forward genetic approach, we found and validated a mutation in Degs2 as causative of increasing susceptibility to colitis and altering the phytoceramide balance in the colon." (PMID 37589563, 2023). "Using forward genetics, we demonstrated that a damaging mutation in Degs2 renders mice susceptible to DSS-induced colitis, which we validated in an independent CRISPR/Cas9-targeted Degs2 mutant strain with a clean genetic background (C57BL/6J)." (PMID 37589563, 2023). "In response to dextran sodium sulfate (DSS)-induced colitis, colonic epithelial cells in DEGS2-deficient mice had increased cell death and decreased proliferation compared to those in wild-type mice." (PMID 37589563, 2023). "Editor's choice: The dual lipid desaturase/hydroxylase DEGS2 contributes to mouse intestinal homeostasis and ameliorates colitis by converting dihydroceramides to phytoceramides." (PMID 37589563, 2023). "The effect of DEGS2 deletion in increasing susceptibility to DSS-induced colitis in mice with intact DEGS1 function indicates that DEGS2 has evolved a non-redundant function that cannot be performed by DEGS1." (PMID 37589563, 2023). "Because phytoceramide is a precursor to phytosphingosine, this finding is in concordance with our findings that lack of DEGS2, and subsequent absence of phytoceramides, in the mouse gut increases susceptibility to colitis." (PMID 37589563, 2023). "DEGS2 is expressed in the intestinal epithelium, and the colitis phenotype is dependent on the non-hematopoietic compartment of the mouse." (PMID 37589563, 2023).
colorectal tumors (1 paper, 2023). "Human DEGS2 has also been found to be increased in colorectal tumors and necessary for the proliferation of cell lines in vitro." (PMID 37589563, 2023).
Crohn disease (1 paper, 2023). A gastrointestinal disorder characterized by chronic inflammation involving all layers of the intestinal wall, noncaseating granulomas affecting the intestinal wall and regional lymph nodes, and transmural fibrosis. "Using the IBD TaMMA, we see DEGS2 mRNA downregulated in Crohn's disease and ulcerative colitis biopsy samples." (PMID 37589563, 2023).
esophageal squamous cell carcinoma (1 paper, 2022). Esophageal squamous cell carcinoma (ESCC) is a type of esophageal carcinoma (EC) that can affect any part of the esophagus, but is usually located in the upper or middle third. "Therefore, the decreased expression of Cer in esophageal squamous cell carcinoma is due to less synthesis (decreased expression of DEGS2) and increased metabolism (increased expression of Sph and SIP)." (PMID 35782075, 2022).
glioma (1 paper, 2022). A benign or malignant brain and spinal cord tumor that arises from glial cells (astrocytes, oligodendrocytes, ependymal cells). "The development of pharmacological activators of DEGS2 could result in novel glioma therapies and will enhance our understanding of the signaling roles of phytoceramides." (PMID 36012521, 2022). "The DEGS2 enzyme is differentially expressed in IDHmut gliomas, which accounts for the presence of phytoceramides that contribute to the sphingolipid rheostat imbalance observed in the IDHmut glioma subtypes." (PMID 36012521, 2022).
Hepatic steatosis (1 paper, 2023). Steatosis is a term used to denote lipid accumulation within hepatocytes. "N-3 PUFAs downregulate Sptlc3 and Degs2-CerS corresponding genes, reducing CerS activity (Cer16:0, Cer18:0, Cer20:0, Cer22:0, and Cer24:0) and decreasing hepatic steatosis in a hyperhomocysteinemia-induced hepatic steatosis mouse model." (PMID 36904216, 2023).
inflammatory bowel disease (1 paper, 2023). A spectrum of small and large bowel inflammatory diseases of unknown etiology. "Analysis of RNA-sequencing data from the IBD Transcriptome and Metatranscriptome Meta-Analysis (TaMMA) framework revealed that, in human inflammatory bowel disease patients, DEGS2 expression was decreased in colonic and small intestinal biopsies." (PMID 37589563, 2023).
meningioma (1 paper, 2023). A generally slow growing tumor attached to the dura mater. "AKT1 meningiomas displayed high relative levels of HTRA1 and transferrin genes relative to KLF4 tumors, while KLF4 tumors overexpressed CEACAM6, DEGS2, and TSPAN12 relative to AKT1 tumors." (PMID 36937440, 2023).
Obesity (1 paper, 2022). Accumulation of substantial excess body fat. "Sgms1 and Degs2, which encode proteins required for the production of sphingolipids, showed highly enriched expression in brain ECs and were upregulated in obesity, particularly in the art cluster." (PMID 36400935, 2022).
tumor (5 papers, 2012 to 2023). "Consistently, clinical data showed that tumor tissues with high DEGS2 levels had more advanced AJCC stage and higher serum CEA levels than those with low DEGS2 levels, which suggested a poor prognosis for CRC patients." (PMID 34363020, 2021). "Tumor xenograft studies showed that DEGS2-WT promoted tumorigenesis, while DEGS2-mut induced an even stronger tumor proliferation ability than DEGS2-WT and the negative control." (PMID 34363020, 2021). "Tumor status induced a significant increase in the expression of CerS2 (p < 0.0001), CerS6 (p < 0.0001), DEGS2 (p < 0.0001), SMPD1 (p < 0.05), and CLN3 (p < 0.0001); and a significant decrease in the expression of UGT8 (p < 0.0001) compared with expression in the corresponding non-tumor tissue." (PMID 26528430, 2015). "Furthermore, to test whether the mutated DEGS2 m6A motif influences CRC tumor growth in vivo, we injected HCT116 cells with DEGS2-WT or DEGS2-mut (with mutation of the potential m6A motif GACT to GGCT)." (PMID 34363020, 2021). "Altogether, the significant differences in the expression of CerS2, CerS6, DEGS2, SMPD1, and UGT8 sphingolipid genes in tumor tissue go hand in hand with elevation of ceramide levels." (PMID 26528430, 2015). "Inter-tumor variation in expression of the dihydroceramide Δ4-desaturases DEGS1 and DEGS2 that introduce a double bond in the sphingolipid backbone to generate ceramide, may also contribute to heterogeneity in the sulfatide saturation index in the iCCA group." (PMID 36630049, 2023). "We found that DEGS2 knockdown repressed tumorigenesis, as indicated by prominently lower tumor weights in the knockdown group than in the negative control group." (PMID 34363020, 2021).
cancer (3 papers, 2021 to 2024). A tumor composed of atypical neoplastic, often pleomorphic cells that invade other tissues. "Dysregulation of DEGS2 might be associated with multiple diseases, such as cancer or inflammation-associated diseases." (PMID 38840260, 2024). "Immunohistochemistry (IHC) analysis of the CRC tissue microarrays showed that DEGS2 was predominantly localized to the cytoplasm and significantly elevated in cancer tissues compared with normal tissues." (PMID 34363020, 2021). "Mechanistically, high DEGS2 expression suppresses Cer synthesis in cancer cells, which mediates the progression of CRC." (PMID 34363020, 2021). "Each successive layer expresses additional cancer marker genes – considering top-1 markers, coexpression hotspot 0 (CH0) expresses DEGS2; CH2 expresses BRINP3; CH10 expresses SUSD3; and CH19 expresses LOXL2." (PMID 37848426, 2023). "Our findings highlight that the function of DEGS2 m6A methylation in CRC and extend the understanding of the importance of RNA epigenetics in cancer biology." (PMID 34363020, 2021). "High DEGS2 expression was not correlated with CD8 T-cell infiltration or PD1 expression (p > 0.05) but was significantly negatively associated with PDL1 expression, which was mainly found on cancer cells and epithelial cells (p < 0.01)." (PMID 34363020, 2021).
infection (1 paper, 2024). The state of being infected such as from the introduction of a foreign agent such as serum, vaccine, antigenic substance or organism. "The result showed that during ALV-J infection, the levels of ASAH1, NAAA, CHKA, PGS1, SGPP1, DEGS2, and SMPD1 genes were significantly increased with infection time." (PMID 38598912, 2024).
intestinal disease (1 paper, 2023). "DEGS2 and phytoceramide levels have previously been shown to correlate with intestinal disease." (PMID 37589563, 2023).
psychiatric disorder (1 paper, 2015). A disorder characterized by behavioral and/or psychological abnormalities, often accompanied by physical symptoms. "Although the DEGS2 gene is expressed in human brain, it is unknown how DEGS2 expression varies during human life and whether it is affected by psychiatric disorders and genetic variants." (PMID 25871975, 2015). "To date, although the DEGS2 gene is expressed in human brain;4 the developmental pattern of DEGS2 expression in the brain and possible alterations in expression in psychiatric disorders has not been examined." (PMID 25871975, 2015).
DEGS2 also shares sentences with these, for which no sentence is quoted: atopic dermatitis (1 paper); bipolar disorder (1); breast carcinoma (1); colon cancer (1); ovarian carcinoma (1); ulcerative colitis (1).